CCR2 (C-C motif chemokine receptor 2)
Diseases named in the same sentence as CCR2 in open-access papers (continued):
Sharing a sentence is not in itself a finding about the gene and the disease.
prostate carcinoma (continued). "A recent study reported that the coffee compound kahweol acetate and cafestol can reduce not only CCL2 secretion but also CCR2 expression on prostate cancer cells." (PMID 33297571, 2020). "In another study to determine the role of CCL2/CCR2 axis in growth of prostate cancer in the bone, knocking down CCR2 abrogated tumor invasiveness." (PMID 32585812, 2020). "Further, CCL2-induced prostate cancer cell chemotaxis was abolished by a CCR2 antagonist, which confirmed that CCR2 is the functional receptor of CCL2." (PMID 32471499, 2020). "In vitro co-culture of prostate cancer cells and macrophages resulted in increased CCL2 and CCR2 levels in prostate cancer cells." (PMID 28039457, 2017). "For instance, CCL2 has been reported to be present in the microenvironment of many types of cancers, and CCR2 has been demonstrated to be upregulated in cancer cells, including prostate cancer cells." (PMID 28039457, 2017). "The fact that phosphorylation of Akt proteins was more effectively inhibited by the CCR4 antagonist than by the CCR2 antagonist also indicates the efficiency of CCR4 in prostate cancer migration and invasion." (PMID 28039457, 2017). "In another study, the authors found that autocrine and paracrine functions of CCL2 are required for prostate cancer growth and invasion, and treatment with a CCR2 antagonist reduced the CCL2-mediated prostate cancer growth and invasion." (PMID 28424660, 2017). "Similar to pancreatic cancer, expressions of CCL2 and CCR2 were present in prostate cancer tissues and led to increased cancer proliferation and invasion through Akt signaling." (PMID 29379802, 2017). "Previously, it has been reported that co-culture of prostate cancer cells and macrophages increased CCR2 and CCL2 expression levels." (PMID 28039457, 2017). "Inhibition of the CCL2–CCR2 or CCL17/CCL22–CCR4 axis by specific antagonists of CCR2 or CCR4 clearly showed suppression of the migration ability of prostate cancer cells." (PMID 28039457, 2017). "Prostate cancer cells also express the primary CCL2 receptor, CCR2, which was increased on prostate cancer cells during clinical progression." (PMID 26317041, 2015). "Lu found that the expression level of CCR2 is much higher in cell stains that have stronger invasiveness, by the detection of CCR2 mRNA and protein expression levels in prostate cancer cells." (PMID 24743888, 2014). "We propose these results indicate the importance of CXCL8-driven CXCR4 and CCR2 expression in the prostate cancer cells, which increases their capacity to respond to each of these stromal-derived chemokines." (PMID 24970800, 2014). "Unexpectedly, the systemic administration of anti-CCL2 antibodies in prostate cancer mouse models only slightly attenuated the proliferation of tumor cells likely due to the "rescue" of the CCR2+ tumor cells by alternate chemokine ligands." (PMID 21943176, 2011). "CCR2 expression has been shown to correlate with prostate cancer progression." (PMID 39146303, 2024). "However, the value of CCL2 and CCR2 as prognostic biomarkers in prostate cancer is unclear and warrant further investigation." (PMID 39199567, 2024). "Furthermore, treating these cells with CCR2 antagonists severely impeded prostate cancer cell migration." (PMID 36836690, 2023). "It regulates prostate cancer motility and proliferation at the site of the bone microenvironment and overexpression of its receptors (CCR2 and CCRL1) may contribute to the progression and biochemical failure of prostate cancer." (PMID 34815548, 2022). "HOXA11-AS-regulated CCL2/CCR2 may modulate the expression of HOXB13/HOXA11-AS-regulated integrins in prostate cancer; however, this interaction requires further investigation in future studies." (PMID 33514011, 2021).
prostate carcinoma (continued). "Because the interaction between cancer cells and the host microenvironment is a vital component of tumorigenesis, the results of our microarray data analysis led us to focus on CCL2/CCR2 for examination of its relationship with HOXA11-AS in both prostate cancer cells and osteoblasts." (PMID 33514011, 2021). "Secondly, CCR2 knockdown significantly diminished the MCP-1-induced prostate cancer cell invasion." (PMID 31137764, 2019). "Moreover, a CCR2 antagonist also inhibited the migration ability of prostate cancer cells induced by U937 and U937-M cells." (PMID 28039457, 2017). "Stimulation of prostate cancer cells with CCL2 was found to induce CCR2 production." (PMID 28039457, 2017). "Given the extensive reports on CCL2 expression in prostate cancer, we chose to utilize CCR2." (PMID 27177227, 2016). "Furthermore, CXCL8 signaling also increased the expression of CXCR4 and CXCR7 (the receptors mediating the biological activity of CXCL12) and CCR2 (a receptor activated by the ligand CCL2) in both PTEN-expressing and PTEN-deficient prostate cancer cells." (PMID 24970800, 2014). "However, the number of prostate cancer patients included in this previous study was limited (n = 96), not targeted to locally advanced tumours, and microarrays were used for immunohistochemical detection of CCR2." (PMID 39199567, 2024). "Our results show that CCL2 and CCR2 are expressed in prostate cancer cells, with CCL2 increased in the serum of prostate cancer patients, but the expression of both CCL2 and CCR2 exhibited no prognostic value." (PMID 39199567, 2024). "In contrast, other studies have suggested a prognostic value for CCR2 and CCL2 with prostate cancer progression." (PMID 39199567, 2024). "Thus, blocking CCL2 with soluble CCR2 fragment or inhibition of CCR2 with blocking antibody could decrease tumor accumulation of MDSCs in the tumor bone metastases model by injecting prostate cancer cells directly into murine tibiae, making it a potential target for anti-tumor therapy." (PMID 37006306, 2023). "Another study reported that CCR2, the receptor for the CCL2 ligand, was increased significantly in prostate cancer cells when treated with CCL2 resulting in elevated cell migration of prostate cancer cells." (PMID 36836690, 2023). "Some studies have shown that CCR2 mediates the cellular effect of MCP‐1 to promote the growth and invasion of prostate cancer." (PMID 33949150, 2021). "Both CCR2 and CCR4 were observed to be expressed in human prostate cancer cell lines and prostate cancer tissues; furthermore, in vitro co-culture of prostate cancer cells and macrophages resulted in increased CCL2 and CCR2 levels in prostate cancer cells." (PMID 30871130, 2019). "Further analyses of protein levels, including western blot and immunocytochemical staining, showed that CCR2 and CCR4 were expressed in all prostate cancer cell lines." (PMID 28039457, 2017). "IHC analysis revealed a significant increase in both CCR2 and CCR4 expressions in prostate cancer cells compared with the expressions in epithelial cells in normal prostate tissues." (PMID 28039457, 2017). "In vitro co-culture of monocyte-lineage cells with prostate cancer cells induce higher expression of CCL2, which promotes the expressions of CCR2 and CCR4 in prostate cancer cells." (PMID 28039457, 2017). "Quantitative reverse transcription polymerase chain reaction (RT-PCR) showed that CCR2 and CCR4 were expressed in all prostate cancer cell lines that we checked." (PMID 28039457, 2017). "CCR2 and CCR4 antagonists clearly inhibited the migration ability of prostate cancer cells, which was induced by CCL2 and CCL17/CCL22." (PMID 28039457, 2017). "We demonstrated the CCR2 and CCR4 gene and protein expressions in prostate cancer cells as well as in human prostate cancer tissues, which are novel findings for CCR4." (PMID 28039457, 2017).
prostate carcinoma (continued). "The increased prostate cancer cell invasion depended on high CCL2 levels and was significantly inhibited by CCL2 neutralizing antibodies or treatment with a biochemical CCR2 inhibitor." (PMID 26317041, 2015). "The monocyte-induced prostate cancer cell invasion was inhibited by CCL2 neutralizing antibodies and by the CCR2 inhibitor, RS102895." (PMID 26317041, 2015). "Several other types of cancer cells, including prostate cancer, breast cancer, and myeloma cells, have also been demonstrated to express CCL2 and its receptor CCR2, both of which are correlated with prostate cancer development." (PMID 21826248, 2011). "Although CCR2 has been targeted experimentally in models of prostate cancer, the impact of CCR2 blockade on human prostate fibrosis has not been examined." (PMID 39748675, 2025). "In conclusion, this study shows that although CCL2 and CCR2 are expressed in prostate cancer, with an increased level of CCL2 in the serum, neither CCL2 nor CCR2 expression has a clinical prognostic value in locally advanced prostate cancer." (PMID 39199567, 2024). "In prostate cancer (PRAD) cells, the expression of CCR2 (the receptor of CCL2) promotes NI, and the expression of CCR2 is closely related to the activity of MAPK and Akt pathways and the migration of cancer cells to chemokine (C-C motif) ligand 2 (CCL2) and DRG." (PMID 36900158, 2023). "In the bone marrow milieu, C-C motif chemokine ligand 2 (CCL2; also known as monocyte chemoattractant protein 1), the primary ligand for C-C motif chemokine receptor 2 (CCR2), is produced in bone marrow osteoblasts, endothelial cells, stromal cells, and prostate cancer cells." (PMID 33514011, 2021). "The NR2C2 also increased prostate cancer invasion by altering TGFβR2/p-Smad3 signalling by decreasing miR-373-3p expression and further, promotes prostate cancer metastasis through upregulation of CCL2/CCR2 signalling." (PMID 33113804, 2020). "In a preclinical study using mouse transplanted with a cabazitaxel-resistant prostate cancer cell line, inhibition of the CCL2–CCR2 axis released cabazitaxel-resistance and suppressed tumor growth in mice treated concurrently with cabazitaxel and CCR2 antagonist." (PMID 33297571, 2020). "Carlumab (CNTO 888), a human monoclonal anti-CCL2 antibody, was well-tolerated but did not block the CCL2/CCR2 axis or show antitumor activity as a single agent in metastatic castration-resistant prostate cancer." (PMID 30871117, 2019). "Interference with this pathway by administration of CCR2 antagonist, CCL2 neutralizing antibody, or PI3 kinase inhibitor or by knockdown of CCL2 in prostate cancer PC3 cells all resulted in decreased tumor formation, smaller tumor size, and less metastases in vivo." (PMID 29379802, 2017). "We first examined CCR2 and CCR4 mRNA expressions in human prostate cancer cells." (PMID 28039457, 2017). "Because the phosphorylation of Akt (Ser473) was more strongly inhibited by the CCR4 antagonist than by the CCR2 antagonist, CCR4 may contribute more to prostate cancer cell migration than CCR2." (PMID 28039457, 2017). "CCR2 and CCR4 were expressed in human prostate cancer cell lines and prostate cancer tissues." (PMID 28039457, 2017). "The aim of this study was to elucidate the role of CCR2 and CCR4 in prostate cancer progression." (PMID 28039457, 2017). "Our results suggest that CCR2 and CCR4 play a critical role in prostate cancer progression." (PMID 28039457, 2017). "Interestingly, CCL2 treatment resulted in significant increases in CCR2 and CCR4 protein levels in prostate cancer cells and promoted recruitment of monocytes into the tumor microenvironment, where they differentiated into TAMs." (PMID 28039457, 2017). "Consistent with our earlier results indicating that CXCL8 signaling up-regulated CCR2 and CXCR4 expression in prostate cancer cells, we observed that the reduction in autocrine CXCL8 expression resulted in a significant decrease in CCR2 and CXCR4 mRNA expression in PC3-120 cells." (PMID 24970800, 2014).
prostate carcinoma (continued). "In prostate cancer cells, the interaction of CCL2 and CCR2 induced STAT3 activation." (PMID 25405202, 2014). "Therefore, our study had greater statistical power and clinical relevance, and highlighted that CCR2 expression has no significant prognostic value in locally advanced prostate cancer." (PMID 39199567, 2024). "Thus, despite experimental data suggesting a role for CCR2 and CCL2 in PNI, in this cohort of locally advanced prostate cancer, we found no significant change in CCR2 or CCL2 protein expression in prostate cancer patients in relation to PNI." (PMID 39199567, 2024). "Here we reviewed recent findings, which link CCL2/CCR2 to the inflammation and cancer pathogenesis, and discussed the therapeutic potential of CCL2/CCR2 axis in cancer treatment based on results from our group and other investigators, with a major focus on prostate cancer." (PMID 32471499, 2020). "However, the role of CCR4 and the relationship between CCR2 and CCR4 in prostate cancer remains unknown." (PMID 28039457, 2017). "Previous studies have demonstrated that Carlumab (CNTO 888), which is a human IgG1κ monoclonal antibody with high affinity and specificity for human CCL2, does not inhibit the CCL2/CCR2 axis or demonstrate antitumor activity as a single agent in metastatic castration-resistant prostate cancer." (PMID 25695619, 2015). "However, neither CCL2 nor CCR2 tissue expression could predict prostate cancer progression, or other clinicopathological parameters including perineural invasion and patient outcome." (PMID 39199567, 2024). "In prostate cancer, a high lipid diet may accelerate tumor cell proliferation by increasing levels of insulin-like growth factor 1, IL-1α, IL-1β, IL -6, or TNF-α or through activation of signaling pathways such as MCP-1/CCR2 (monocyte chemoattractant protein-1/C-C Motif Chemokine Receptor 2)." (PMID 38028534, 2023). "Our study examined the expression of CCR2 and CCL2 protein in locally advanced prostate cancer and found that they have no prognostic value in the disease." (PMID 39199567, 2024). "Although MCP-1/CCL2 was produced by both monocytes and prostate cancer cells, it appears that the CCL2 production was not simply driven by a positive feedback loop, since the CCR2 inhibitor RS102895 did not affect the CCL2 levels in the co-cultures." (PMID 26317041, 2015).
myocardial infarction (60 papers, 2010 to 2026). Gross necrosis of the myocardium, as a result of interruption of the blood supply to the area, as in coronary thrombosis. "Using data from 1.5M individuals we found that heterozygous carriers of a rare experimentally confirmed damaging CCR2 variant (M249K) are at lower lifetime risk of myocardial infarction and coronary artery disease." (PMID 37645892, 2024). "Carriers of 45 predicted damaging or loss-of-function CCR2 variants (n=787 individuals) were at lower risk of myocardial infarction and coronary artery disease." (PMID 37645892, 2024). "Single nucleotide polymorphisms (SNPs) in the promoter of CCL2, CCL2-2518G, and in the open reading frame of CCR2, CCR2-V64I, have been associated with increased risk of myocardial infarction in humans." (PMID 24741577, 2014). "Additionally, it has been observed that CCR2‐deficient mice demonstrate an intensification in cellular clearance following myocardial infarction, suggesting an enhanced ability to remove damaged cells from the affected area." (PMID 39223947, 2024). "CCR2 rs1799864, a SNP causing an isoleucine-for-valine substitution at position 64 in the CCR2 receptor on chromosome 3, was found to be associated with ischemic cardiomyopathy and myocardial infarction in Czech populations." (PMID 22769019, 2012). "CCR2+ monocytes are known to be involved in the progression of neuropathological processes and cognitive dysfunction after myocardial infarction via CCR2-dependent recruitment to the CNS." (PMID 41537429, 2026). "Under pathological cardiac conditions, such as myocardial infarction and heart failure, CCR2+ macrophages exhibit potent pro-inflammatory functions." (PMID 40429668, 2025). "From a therapeutic perspective, targeting CCR2+ macrophages represents a promising strategy to effectively reduce post-myocardial infarction inflammation, alleviate fibrosis, and improve cardiac function." (PMID 40429668, 2025). "Studies indicate that a higher prevalence of CCR2+ macrophages in the heart correlates with a poorer prognosis after experiencing a myocardial infarction." (PMID 39223947, 2024). "During the acute inflammatory phase of myocardial infarction (MI), a substantial influx of CCR2+ monocytes occurs, accompanied by the infiltration of their derived CCR2+ macrophages." (PMID 39223947, 2024). "Reduced transcription of CCL2, expression of CD163+ macrophages, and modulation of immune response factors, including IL-1, PBMC influx, TNF-α, GM-CSF levels, and CD73+ and CCR2+ monocytes, further support EV’s therapeutic potential for myocardial infarction." (PMID 38790361, 2024). "Cells expressing CCR2, like monocyte, T cells, or B cells are present in large numbers in inflammatory states following an acute event such as myocardial infarction." (PMID 37242772, 2023). "For example, induction of myocardial infarction in CCR2−/− mice known to have reduced inflammatory monocyte recruitment results in reduced collagen content in the scar in association with decreased infarction size and a preserved ejection fraction." (PMID 36498897, 2022). "Inhibition of monocyte recruitment by blocking the CCL2 and CCR2 signaling pathways reduces excessive inflammation, myocardial infarction and atherosclerosis is protective in a sclerosis-like mouse model." (PMID 36247005, 2022). "While CCR2– TRMs are abundant in the healthy state and instrumental for repair following damage, e.g. after myocardial infarction (MI), CCR2+ TRMs are rare in healthy states but quickly recruited upon injury and frequently mediating disease." (PMID 35548426, 2022). "The results suggest that CCR2 inhibitors are expected to be used in the targeted therapy of clinical myocardial infarction." (PMID 36196399, 2022). "After myocardial infarction, Ly6Chigh, CCR2+ monocytes infiltrate into the heart and differentiate into CCR2+ macrophages to promote pro-inflammatory responses, collateral tissue damage, and ultimately lead to cardiac fibrosis and heart failure." (PMID 36275654, 2022).